IL17A (interleukin 17A)
Diseases named in the same sentence as IL17A in open-access papers (continued):
Sharing a sentence is not in itself a finding about the gene and the disease.
osteoporosis (continued). "Regarding osteoblasts, deleterious effects of anti-IL-17A on bone mass could be a concern although the effects of IL-17A on osteoporosis in the SKG mouse model were unclear." (PMID 32448352, 2020). "In postmenopausal osteoporosis patients, serum IL-17A is significantly higher, while the IFN-γ and IL-4 are significantly lower, suggesting osteoporosis may be more associated with the Th17 cells rather than the Th1 or Th2 cells." (PMID 33408628, 2020). "In this study, we provide an explanation for the discrepancies in previous literature and show for the first time that loss of IL-17A has differential effects on OVX-induced osteoporosis; with IL-17A being important for cortical but not trabecular bone loss." (PMID 32231224, 2020). "However, IL-17A is also a potent activator of osteoclast differentiation, which triggers osteoporosis." (PMID 32448352, 2020). "Similarly, IL-17A levels were higher in PHPT women with osteopenia with respect to PHPT women with osteoporosis." (PMID 32256191, 2020). "In vivo, IL-17A is not required for normal bone homeostasis but plays an important role in bone loss notably in an ovariectomized mouse model of osteoporosis." (PMID 31485194, 2019). "The effect of IL-17A on the bone has been studied in animal models of osteoporosis." (PMID 31485194, 2019). "This T-cell-induced OCL differentiation could be inhibited by IL-17 blockade suggesting the importance of IL-17A in osteoporosis." (PMID 26734007, 2015). "Moreover, the expression of TNF-α and IL-17A in old rats after long-term drinking was significantly higher than that in the young rats, indicating that the effects of alcohol on the inflammatory response to promote osteoporosis was more significant in the old rats." (PMID 34336709, 2021). "The aim was to compare levels of AGEs and IL-17A in WS and peri-implant clinical and radiographic status of patients with and without osteoporosis at 6-years’ follow-up." (PMID 36424586, 2022). "Levels of whole salivary IL-17A in patients without and with osteoporosis were 4.6 ± 0.3 and 5.1 ± 0.8 pg/ml, respectively." (PMID 36424586, 2022). "While secukinumab (anti-IL-17A) has not been evaluated for the treatment of osteoporosis, this finding highlights the complex nature of targeting cytokines in preventing bone loss." (PMID 34276675, 2021). "By contrast, circulating IL-17A was undetectable in premenopausal women without osteoporosis, in line with previous reports, and consistent with the inhibitory effect of estrogens on IL-17A release." (PMID 32256191, 2020). "Moreover, results from laboratory-based investigations showed that whole salivary levels of AGE and IL-17A were comparable and within minimum detection range among individuals without and with osteoporosis." (PMID 36424586, 2022). "A review of indexed literature also showed no studies that assessed whole salivary IL-17A and AGE levels among patients with and without osteoporosis." (PMID 36424586, 2022).
type 2 diabetes (83 papers, 2012 to 2026). "Serum IL‐17A level is associated with renal function decline and diabetic retinopathy in patients with type 2 diabetes in a Chinese Han population." (PMID 39946217, 2025). "Evidence suggested that IL‐17A was associated with renal function in type 2 diabetes." (PMID 39946217, 2025). "In patients with type 2 diabetes, the distribution of serum IL‐17A concentration was skewed (p < 0.0001)." (PMID 39946217, 2025). "Collectively, this provides strong evidence that IL-17A plays a pivotal role in Type II diabetes induced diabetic retinopathy." (PMID 36674854, 2023). "While examining the efficacy of anti-IL-17A as a potential therapeutic in a short-term Type I and a long-term Type II diabetes model; using different routes of administration of anti-IL-17A treatments." (PMID 36674854, 2023). "Contrary, it was reported that IL-17A levels in plasma and urine were reduced in patients with advanced diabetic nephropathy; administration of low-dose IL-17A prevented diabetic nephropathy in models of type 1 and type 2 diabetes." (PMID 32961903, 2020). "Interleukin-17 (IL-17), particularly IL-17A, is a pro-inflammatory cytokine predominantly produced by Th17 cells and is increasingly recognized for its involvement in the immunopathogenesis of both type 1 and type 2 diabetes." (PMID 40804870, 2025). "Increased production of IL-17A in the periodontal lesions of patients with type 2 diabetes might have affected the development of diabetic retinopathy via the IL-17A receptor in the retina." (PMID 33050355, 2020). "This study investigates the relationship between serum IL‐17A levels and diabetic kidney disease (DKD) in individuals with type 2 diabetes." (PMID 39946217, 2025). "We found that at the end of treatment, XOMA052 was able to alleviate chronic inflammation in type 2 diabetes by down-regulating the production of IFN-γ and IL-17a in peripheral blood, reducing inflammatory cytokines TNF-α, IL-1β, and IL-6, and reducing β cell apoptosis and promoting proliferation." (PMID 40066372, 2025). "Notably, the findings define the role of IL-17A in Type II diabetes-induced non-proliferative diabetic retinopathy, while further defining the efficacy of anti-IL-17A as a potentially novel therapeutic for non-proliferative diabetic retinopathy." (PMID 36674854, 2023).
bladder cancer (82 papers, 2011 to 2026). "For example, IL-17 F exerts effects on angiogenesis, while the elevated vessels in turn contribute to elevation of IL-17A or IL-17 F production in bladder cancer, which formats a positive feedback to promote malignant proliferation." (PMID 27716046, 2016). "IL-17A expression located mainly in mononuclear cells, transitional epithelial cells, malignant cells and vascular endothelial cells in bladder cancer." (PMID 27716046, 2016). "Clearly other experiments need to be done to confirm the roles of IL-17A and IL-17E signals in bladder cancer occurrence and development." (PMID 27716046, 2016). "For example, elevated expressions of IL-17A, IL-17 F and IL-17RC and increased numbers of macrophages were observed in bladder cancer." (PMID 27716046, 2016). "We compared expression and location of IL-17 cytokine family IL-17A, IL-17E and IL-17 F and their receptors IL-17RA, IL-17RB and IL-17RC in tissues derived from subjects with cystitis, bladder polyp and bladder cancer in parallel." (PMID 27716046, 2016). "The results of a complex study on the immunoreactivity of the ligands and receptors of the IL-17 family in patients with bladder cancer showed significantly elevated IL-17A, IL-17F, and IL-17RC immunoreactivity in the bladder cancer group but decreased IL-17E, IL-17RA, and IL-17RB immunoreactivity." (PMID 37371647, 2023). "The levels of serum IL-17A are elevated in gastric and bladder cancer patients." (PMID 28035060, 2017). "In the present study, expression of IL-17A and IL-17 F increased but IL-17RA decreased in bladder cancer, suggesting that IL-17A and IL-17 F are possibly expressed by different profiles of cellular populations and mainly through binding IL-17RC to exert biological effects." (PMID 27716046, 2016). "Compared with subjects with cystitis, immunoreactivity for IL-17A, IL-17 F and IL-17RC was significantly elevated in the group of bladder cancer (p < 0.01), while immunoreactivity of IL-17E, IL-17RA and IL-17RB, and the infiltrating neutrophils were decreased (p < 0.05)." (PMID 27716046, 2016). "One possible explanation may be that IL-17A and IL-17 F and IL-17RC can be expressed by these macrophages in bladder cancer." (PMID 27716046, 2016). "In contrast to IL-17A, global IL-17RA immunoreactivity was significantly elevated in cystitis and polyp compared with those of bladder cancer (p = 0.001 and p = 0.001, respectively), while global IL-17RA immunoreactivity was significantly higher in polyps than those of cystitis (p = 0.015)." (PMID 27716046, 2016). "For example, it has been shown that IL-17A transcripts in peripheral blood mononuclear cells and serum concentrations of IL-17A were significantly higher in peripheral blood mononuclear cells in subjects with bladder cancer than those of controls." (PMID 27716046, 2016). "Additionally, other changed abnormal structural cells such as endothelial cells and fibroblasts were also observed in bladder cancer, which might contribute to the increases of immunoreactivity for IL-17A, IL-17 F and IL-17RC." (PMID 27716046, 2016). "In addition, close correlations of expression of IL-17A-IL-17RA and IL-17E-IL-17RB suggest that different signaling of IL-17A-IL-17RA and IL-17E-IL-17RB might play an important role in bladder cancer." (PMID 27716046, 2016). "The purpose of this study was to assess the expression of CXCR2, IL-17RA, and IL-17RC genes at the mRNA level as well as tissue and serum levels of IL-17A, vascular endothelial growth factor (VEGF), and transforming growth factor β (TGF-β) in patients with bladder cancer (BC) compared to control." (PMID 38515019, 2024). "Although we observed that some immunoreactivity for IL-17A and IL-17 F located in malignant cells, however, until far, there is lack of systemic study whether malignant cells in bladder cancer express IL-17A or IL-17 F." (PMID 27716046, 2016).
endothelial dysfunction (82 papers, 2012 to 2025). In vascular diseases, endothelial dysfunction is a systemic pathological state of the endothelium (the inner lining of blood vessels) and can be broadly defined as an imbalance between vasodilating and vasoconstricting substances produced by (or acting on) the endothelium. "Other pathogenic effects of IL-17A on endothelial dysfunction include the induction of the gene expression of chemokines and pro-inflammatory mediators, including IL-8, CCL20, IL-6 and IL-15." (PMID 33322218, 2020). "Elevated Th17 cells and IL-17a levels are linked to endothelial dysfunction and CVD in PLWH." (PMID 39000373, 2024). "As IL-17A was shown to modulate the recruitment of neutrophils during inflammation, we expected vascular immune cell infiltration to the underlining reason for the observed endothelial dysfunction." (PMID 31396305, 2019). "Interestingly, administration of recombinant IL-17A results in increased systolic blood pressure in mice, and this was associated to endothelial dysfunction and vascular damage." (PMID 31572188, 2019). "Overexpression of IL-17A in the skin has been shown to induce systemic endothelial dysfunction, vascular oxidative stress, hypertension, and increased mortality." (PMID 41002407, 2025). "In addition to ROS production, IL-17A may cause endothelial dysfunction via Rho-kinase activation." (PMID 36835372, 2023). "In summary, chronic exposition to T cell-derived IL-17A led to a significant endothelial dysfunction." (PMID 31396305, 2019). "Our data demonstrate that T cell-derived IL-17A can disrupt the oxidant-antioxidant balance and induce oxidative stress leading to endothelial dysfunction." (PMID 31396305, 2019). "Considering that IL-17a is a crucial component in the mechanisms responsible for endothelial dysfunction in this TLR7-driven lupus autoimmunity model, our group then focused on the possible changes induced by DMB on the SLE-linked endothelial dysfunction." (PMID 35052589, 2021). "Cytokines, including TGF-β1, TNFα, IFNγ, IL-1β, and IL-17A, may regulate blood pressure through effects on endothelial dysfunction, salt and water balance, and sympathetic regulation." (PMID 31572188, 2019). "Additionally, the elevated inflammatory cytokines, including IL-6, IL-8, and IL-17A, may further exacerbate endothelial dysfunction." (PMID 40557145, 2025). "This inflammatory response is further enhanced by increased IL-17A, TNF-α, IL-6, and other mediators involved in developing endothelial dysfunction." (PMID 40137170, 2025). "Cytokines such as TNF-α, IL-6, IL-17A, CXCL9, CXCL10, and VCAM-1 are often elevated in both MASLD and SAH, playing crucial roles in immune cell recruitment, endothelial dysfunction, and fibrogenesis." (PMID 40977717, 2025). "Systemically, IL-17A contributes to vascular dysfunction and SAH by promoting oxidative stress, endothelial dysfunction, and vascular stiffness." (PMID 40977717, 2025). "To further explore the role of IL-17a in endothelial dysfunction induced by IMQ, we incubated for 6 h with anti-IL-17a antibody." (PMID 34573058, 2021). "Pro-inflammatory T cell–derived cytokines such as IFN-γ and TNF-α (from CD8+ and CD4+Th1) and IL-17A (from the γδ-T cell and CD4+Th17) exacerbate hypertensive responses mediating both endothelial dysfunction and cardiac, renal, and neurodegenerative injury." (PMID 31321561, 2019).
ovarian carcinoma (81 papers, 2011 to 2025). A malignant neoplasm originating from the surface ovarian epithelium. "For example, mouse CD27− γδ T cells that secrete IL-17A facilitate ovarian cancer growth by mobilizing pro-tumor small peritoneal macrophages, whereas IL-17–devoid γδ T cells are beneficial in ovarian cancer." (PMID 40148988, 2025). "For example, IL‐17A, a vital proinflammatory cytokine, has been found to upregulate FABP4 to realize more fatty acid uptake through the IL‐17A/IL‐17RA/p‐STAT3/FABP4 axis to help ovarian cancer cell growth and metastasis in an adipose‐rich environment." (PMID 37605299, 2023). "The FABP4 upregulation can also be induced by cytokine IL-17A secreted by IL-17A-producing cells via p-STAT3 signaling in the metastatic process of ovarian cancer to omentum." (PMID 35899119, 2022). "IL-17A is a multi-effect cytokine, and its expression is related to the pathological differentiation level and lymph node metastasis of ovarian cancer patients." (PMID 35411258, 2022). "Several lines of evidence indicate that IL-17A promotes the self-renewal of CD133+ cancer stem-like cells in ovarian cancer." (PMID 33649532, 2021). "It was interesting to observe in our study that there was a significantly higher concentration of IL-17A in both the plasma and PF of patients with ovarian cancer, compared to the group with benign ovarian tumors." (PMID 32148497, 2020). "The plasma IL-17A concentration was higher (p=0.05) compared to that detected in the PF of patients with ovarian cancer." (PMID 32148497, 2020). "Our own research showed significantly higher IL-17A concentration in the plasma of ovarian cancer patients, compared to that in peritoneal fluid." (PMID 32148497, 2020). "The highest concentration of IL-17A was detected in the plasma of ovarian cancer patients and it was significantly higher (p < 0.0001) compared to both the group of benign ovarian tumors and the control." (PMID 32148497, 2020). "The IL-17A concentration in the PF of ovarian cancer patients was significantly higher (p < 0.0001) compared to the group with benign ovarian tumors." (PMID 32148497, 2020). "In line with the mouse data demonstrating the transdifferentiation of Th17 cells into IL-17negFoxp3+ cells, Foxp3 expression is induced in human IL-17A-producing ovarian cancer TALs when CD4+IL-17+ cells are restimulated under Treg-driving conditions." (PMID 28290453, 2017). "CD4+ T cells infiltrating the ovarian cancer ascites demonstrate a propensity towards either Foxp3-expressing or IL-17A-producing phenotype, implying that the developmental pathways of Treg and Th17 cells are mutually exclusive." (PMID 28290453, 2017). "Similar to the mouse IL-17A+Foxp3+ T cells, human ovarian cancer ascites-infiltrating IL-17A+Foxp3+ T cells show upregulation of neuropilin, GARP and ST2 compared with IL-17A+Foxp3neg T cells, and present a phenotype similar to IL-17AnegFoxp3+ T cells." (PMID 28290453, 2017). "Both TGF-β and ovarian cancer conditioned medium upregulate Foxp3 expression in human CD4+IL-17A+ TALs compared with control and Th17-driving conditions." (PMID 28290453, 2017). "IL-17A has been found in many types of cancer, e.g., ovarian cancer and pancreatic cancer." (PMID 32855976, 2020). "Increasing studies have illustrated that Th17/IL-17a axis may promote the progression of solid tumors (lung, liver and ovarian cancers) and hematologic cancers (chronic lymphocytic leukemia and myeloma)." (PMID 32554855, 2020). "Moreover, IL-17A has been detected in multiple cancer entities, such as ovarian cancer and pancreatic cancer." (PMID 28035060, 2017). "Recently, however, it has been reported that the levels of Th17 cells and the levels of IL-17A in ascites were reduced in more advanced diseases and positively predicted patient outcome in human ovarian cancer because Th17 cells contributed to anti-tumor immunity." (PMID 23372655, 2013).
ovarian carcinoma (continued). "Specifically, IL-17A activated STAT3 phosphorylation to promote FABP4 expression, thereby increasing ovarian cancer cell proliferation." (PMID 35216285, 2022). "Human recombinant IL-17A induces fatty acid uptake by upregulating FABP4 expression in OvCa cells and consequently contributes to the progression and metastasis of ovarian cancer cells." (PMID 35216285, 2022). "CD4+IL-17A+ TALs restimulated in ovarian cancer conditioned medium, but not in the presence of Th17-driving cytokines or TGFβ, demonstrate increased production of IL-10." (PMID 28290453, 2017). "In ovarian cancer, γδ T cells and their Vδ1 subset produced IL-17A, impaired antitumor responses, and enhanced immunosuppressive activities, as documented by their ability to inhibit the proliferation of naive CD4+ T cells upon co-culture with ovarian cancer tissue supernatants." (PMID 36793708, 2023). "Interestingly, TGF-β, but not ovarian cancer conditioned medium, also promotes Il17a expression in CD4+IL-17A+ TALs, suggesting that TGFβ might be promoting IL-17A+Foxp3+ cells while the tumour microenvironment promotes exTh17 Foxp3+ T cells." (PMID 28290453, 2017).